EZH2 (enhancer of zeste 2 polycomb repressive complex 2 subunit)
Diseases named in the same sentence as EZH2 in open-access papers (continued):
Sharing a sentence is not in itself a finding about the gene and the disease.
lupus (continued). "Ezh2 gene deletion or pharmacological Ezh2 inhibition suppresses autoantibody production and GC formation in bm12 lupus-like cGVHD and decreases affinity maturation and isotype switching in response to immunization with a T cell-dependent antigen." (PMID 32503684, 2020). "Our study suggests that Ezh2-mediated epigenetic alteration is a primary promoter of autoAb production in the bm12 cGVHD model of lupus." (PMID 32503684, 2020). "Enhancer of zeste homolog 2 (EZH2), an epigenetic modulator important to T cell activation and differentiation, is over-activated in lupus CD4+ T cells." (PMID 32308657, 2020). "In CD4+ T cells of patients with lupus, upregulation of EZH2 and H3K27me3 alters the methylation status, and overexpression of EZH2 promotes CD4+ T cells adhesion to endothelial cells through demethylation and upregulation of JAM-A, thus increasing disease activity in lupus." (PMID 35559246, 2022). "Based on the research of EZH2 in lupus patients and mouse models, EZH2 inhibition may become a promising treatment for SLE." (PMID 36313363, 2022). "Given the effect of the cooperation of BCL-6 and EZH2 on miR-142-3p/5p expression in CD4+ T cells in lupus, we wondered whether EZH2 could be a therapeutic target for lupus treatment." (PMID 35637283, 2022). "Further studies in bm12-induced lupus and MRL/lpr spontaneous lupus with two structurally related Ezh2 selective small molecule inhibitors, GSK503 and GSK126, respectively, demonstrated significantly reduced autoAb production, GC formation, and improved lupus nephritis." (PMID 35159315, 2022). "Therefore, 3-DZNep elicited inhibition of EZH2 can effectively prevent the progression of renal damage in lupus." (PMID 33679454, 2021). "In addition, levels of two microRNAs (miR-101 and miR-26a) targeting and regulating EZH2 in CD4+ T cells of lupus patients were negatively correlated with lupus disease activity." (PMID 33679454, 2021). "In lupus patients, overexpression of EZH2 leads to the methylation of JAM-A (junctional adhesion molecule A), which may increase the migration of T cells and lead to the invasive exosmosis of T cells." (PMID 33679454, 2021). "Upregulation of Ezh2 during cGVHD raised the possibility that suppression of Ezh2 might decrease the immunological sequelae of cGVHD, including its lupus-like features." (PMID 32503684, 2020). "Pharmacological inhibition of Ezh2, like genetic Ezh2 deficiency, ameliorated autoantibody production in the bm12 model of lupus-like cGVHD, raising the possibility that Ezh2 could serve as a therapeutic target." (PMID 32503684, 2020). "Inhibition of Ezh2 by GSK503 significantly reduced autoantibody production in our lupus model." (PMID 32503684, 2020). "Although this model should also be useful for determining whether Ezh2 can suppress established autoimmunity, studies in spontaneous lupus models, such as the NZB/W mice, will be needed prior to clinical trials in human SLE patients." (PMID 32503684, 2020). "The decreased severity of bm12 cGVHD when Ezh2 genetically deleted in donor T cells and previous observations that Ezh2 is upregulated in GC T and B cells suggested that pharmacological inhibition of Ezh2 might suppress lupus-like features of bm12 cGVHD." (PMID 32503684, 2020). "Additionally, EZH2 is highly expressed in naïve CD4+ T cells in lupus patients compared to healthy controls and positively correlates with lupus disease activity." (PMID 30545086, 2018). "The expression of Ezh2 mRNA is significantly downregulated in patients with active systemic lupus erythematosus, which could be one of the reasons for their abnormal cytokine production." (PMID 21624129, 2011). "In systemic lupus erythematosus, the immune tolerance of B cells is disrupted, leading to overproduction of autoantibodies and exacerbation of autoimmune responses, and inhibition of EZH2 repairs this immune tolerance and reduces autoantibody production in pristane-induced lupus mice." (PMID 40264032, 2025).
lupus (continued). "EZH2 inhibition was demonstrated to restore the cytotoxic response of CD8 T cells in patients with systemic lupus erythematosus (SLE), inhibiting the incidence of infection and thus reducing death resulting from infection." (PMID 36195655, 2022). "Recent studies have identified that the expression of EZH2 is altered in SLE patients, and targeted therapy against EZH2 ameliorates the clinical performance of lupus mice." (PMID 36313363, 2022). "Ezh2 inhibition may be useful for the treatment of lupus and other autoimmune disorders." (PMID 32503684, 2020). "EZH2 is overexpressed in CD4+ T and CD19+ B cells of lupus patients and promotes the adhesion, migration, extravasation of CD4+ T cells, and plasmablast differentiation." (PMID 35795677, 2022). "Ezh2 inhibition by DZNep significantly reduces renal inflammation and improves the survival of MRL/lpr spontaneous lupus mice before and after the disease onset." (PMID 35681462, 2022). "In lupus-prone MRL/lpr mice, intraperitoneal administration of 3-deazaneplanocin A (DZNep), an EZH2 inhibitor, improved survival and significantly reduced anti-dsDNA antibody levels." (PMID 36220996, 2022). "Inhibition of Ezh2 by DZNep improved survival and significantly reduced renal inflammation in MRL/lpr spontaneous lupus mice before and after disease onset." (PMID 35159315, 2022). "It has been reported that unregulated EZH2 activation in CD4+ T cells leads to T cell activation and non-Th1 immune responses, prior to transcription activity, and is related to lupus activity." (PMID 33679454, 2021). "We explored if EZH2 inhibitor could treat IFN-I-driven organ damage (lupus nephritis) in SLE mouse model." (PMID 33868295, 2021). "Blocking EZH2 by 3-DZNep and GSK126 can effectively inhibit the adhesion of lupus T cells to human microvascular endothelial cells." (PMID 33679454, 2021). "Further, inhibiting EZH2 significantly improved survival and ameliorated lupus-like disease in MRL/lpr lupus-prone mice." (PMID 32395334, 2020). "EZH2 is overexpressed in CD4+ T cells from patients with systemic lupus erythematosus (SLE)." (PMID 32395334, 2020). "The application of EZH2 inhibitors improved lupus-like symptoms in MRL/lpr mice, lowered the production of type I interferon in NZW/NZB F1 mice and reduced GC formation and autoantibody secretion in bm12 induced lupus-like cGVHD." (PMID 36313363, 2022). "In contrast, GSK503 inhibits Ezh2 much more strongly than it inhibits other histone methyltransferases, yet still effectively blocks bm12-induced lupus-like cGVHD in mice without obvious adverse effects." (PMID 32503684, 2020). "EZH2 is almost exclusively increased in plasmablasts, but not in naive and memory B cells in lupus." (PMID 36313363, 2022). "Suppression of EZH2 expression in CD4+ T cells might be mediating at least some of the therapeutic effects observed with blocking mTOR activation and with glycolysis inhibitors in SLE and lupus-prone animal models." (PMID 32395334, 2020). "Based on these observations, it is reasonable to hypothesize that Ezh2 activity promotes lupus pathogenesis through non-canonical activation of the STAT3 pathway as well as through its methyltransferase activity." (PMID 32503684, 2020). "The histone methyltransferase Ezh2 contributes to epigenetic regulation of gene expression, is highly expressed in germinal center (GC) B cells and follicular T helper (TFH) cells, and may be involved in lupus pathogenesis." (PMID 32503684, 2020).
metastatic prostate carcinoma (24 papers, 2005 to 2026). A carcinoma that arises from the prostate gland and has spread to other anatomic sites. "In metastatic prostate cancer, EZH2 upregulated oncogenes and loss of EZH2 inhibited the proliferation of cancer cells." (PMID 25159232, 2014). "PRC2/EZH2 inhibitors (PRC2i/EZH2i) are promising for the treatment of advanced cancers including metastatic prostate cancer." (PMID 41842971, 2026). "Significant reverse correlation between HNF1B and EZH2 protein levels was also readily identified by IHC analyses in 17 cases of in-house collection of metastatic prostate cancer samples (r = −0.672; P = 0.031)." (PMID 31636385, 2020). "For example, in metastatic prostate cancer, both the content of EZH2 messenger RNA and EZH2 protein are increased." (PMID 33299862, 2020). "Both mRNA and protein levels of EZH2 were high accompanied with low HNF1B-expressing in the metastatic prostate cancer cell lines PC-3 and DU145." (PMID 31636385, 2020). "There is also increasing evidence for lineage plasticity between adenocarcinoma and neuroendocrine phenotypes in metastatic prostate cancer, induced upon anti-androgen therapy and partially reversed through epigenetic interventions such as EZH2 inhibition." (PMID 29132337, 2017). "As expected, hierarchical clustering of the transcriptome data revealed that the EZH2 transcript is part of a cluster of genes highly expressed in metastatic prostate cancer." (PMID 26637281, 2015). "EZH2 is overexpressed in metastatic prostate cancer and has been shown to promote cell proliferation and metastasis." (PMID 25341040, 2014). "miR-101 locus is lost in metastatic prostate cancer, which leads to up-regulation of EZH2, indicating that miRNA-101 acts as a EZH2 repressor." (PMID 22408395, 2012). "EZH2 is up-regulated in many cancers, including clinically localized and metastatic prostate cancers." (PMID 20479932, 2010). "For example, EZH2 up-regulates oncogenes in metastatic prostate cancer and may be a valuable prognostic indicator of patient outcomes." (PMID 26848980, 2016). "Another report demonstrated that miR-101 plays a major role in EMT through enhancement of a histone methyl transferase Zeste homolog (EZH2) whose expression was found elevated in a subset of aggressive, clinically localized prostate cancers and almost all metastatic prostate cancers." (PMID 22408395, 2012). "The findings published to date, therefore, can explain EZH2 upregulation in only a subset of cases of primary and metastatic prostate cancer, and the mechanisms by which EZH2 is upregulated in PIN lesions and in a subset of early carcinomas have not been fully elucidated." (PMID 21941025, 2011). "EZH2 is overexpressed in metastatic prostate cancer and is a marker of aggressive diseases." (PMID 22191037, 2011). "Previous studies have shown that EZH2 was able to bind to the human ADRB2 promoter and repressed ADRB2 expression, which promoted metastatic prostate cancer." (PMID 37128280, 2023). "It is known that EZH2 is crucial in promoting EMT, a process that is connected to metastasis, and its overexpression has been reported in both metastatic prostate cancer, NEPC and CRPC." (PMID 31636385, 2020). "Expression-microarray studies have also identified EZH2 as a gene overexpressed in hormone-refractory metastatic prostate cancer: notably, patients with clinically localised prostate cancer that express EZH2 have a worse prognosis than those that do not express the protein." (PMID 15583692, 2005). "In this paper, we explore the expression of two proteins, i.e. EZH2 and AMACR known to be differentially expressed in non aggressive or localized tumors (class 1 or negative class) versus aggressive or metastatic prostate cancers (class 2 or positive class)." (PMID 17125514, 2006).
brain tumors (23 papers, 2010 to 2025). "Finally, we identified pathways associated with EZH2 expression in brain tumors." (PMID 20920292, 2010). "Key alterations among KMTs in pediatric brain tumors include aberrant expression of EZH2, NSD1, SETD1A, SMYD3, MLL2 (KMT2D), and G9A (EHMT2)." (PMID 40556679, 2025). "Another HMT pivotal in brain tumor formation is Enhancer of Zeste Homolog 2 (EZH2), a key component of Polycomb Repressive Complex 2 (PRC2)." (PMID 40599851, 2025). "We then tested if GSK126, a small molecule pharmacologic inhibitor of EZH2, can reverse histone methylation in brain tumor cells in vitro." (PMID 34336705, 2021). "In accord with a context-dependent role of EZH2 as a tumor suppressor or an oncogene, targeted disruption of EZH2 by shRNA or EZH2 inhibitory drugs strongly suppressed the proliferation of other models of pediatric brain tumors." (PMID 29178021, 2018). "Network analysis revealed that brain tumor cells overexpressing EZH2 display activation of SC- and cell cycle-specific pathways, and consistent with this data, differentiation genes are silenced by PRC2." (PMID 20920292, 2010). "In keeping with previously published data, our results suggest that EZH2 is both a prognostic factor and a promising therapy target in brain tumors." (PMID 20920292, 2010). "Since EZH2 is essential for NCSC self-renewal, and due to our results showing that EZH2 is overexpressed in brain tumors, we investigated the prognostic role of EZH2 in gliobalstoma." (PMID 20920292, 2010). "EZH2 expression increases with tumor grade in adult and pediatric brain tumors, and is a poor prognostic factor." (PMID 20920292, 2010). "The most studied methyltransferase in pediatric brain tumors is EZH2, a critical component of PRC2." (PMID 40556679, 2025). "EZH2 inhibitors are currently tested for cancer therapy and brain permeable derivatives may offer new avenues in the treatment of brain tumors." (PMID 37892185, 2023). "Similarly, the in vivo tumorigenesis assay indicated that EZH2-92aa KD alone transiently inhibited brain tumour growth in mice (for ~20 days)." (PMID 35970825, 2022). "Enhancer of zeste homolog 2 (EZH2), which is part of a Polycomb repressor complex that methylates lysine 27 of histone H3 (H3K27), leading to transcription inhibition, is often mutated or highly expressed in pediatric brain tumors." (PMID 32754588, 2020). "Moreover, EZH2 expression significantly increased with tumor grade in both adult and pediatric brain tumors." (PMID 20920292, 2010). "Although the overall EZH2 levels may decrease with age, certain stimuli related to diseases such as neuroinflammation, brain tumors or acute injury of the aged brain may induce EZH2 expression, especially in astrocytes and microglia, increasing its levels locally." (PMID 40723311, 2025). "Collectively, our findings from both the primary brain tumor cohort and the I2A cell line suggest that the SMARCB1 deficiency may prime ATRTs for the induction of viral mimicry, a response that can be further enhanced upon EZH2 inhibition." (PMID 39472584, 2024). "Therefore, proliferation and invasion of brain tumors are affected by miRNA/EZH2 axis." (PMID 35236381, 2022). "In brain tumors, global loss of H3K27me3 may be explained by KDM6B over-expression, leading to H3K27me3 demethylation, and/or EZHIP over-expression that leads to inhibition of EZH2, resulting in global loss of H3K27me3." (PMID 34399838, 2021). "Notably, we could confirm BMI1 and EZH2 down-regulation in the brain tumor during the treatment period and their reactivation 15 days post-treatment in an animal showing relapse." (PMID 31934644, 2020). "Overall, epigenetic modification changes of H3K27me3 by dysregulation of EZH2/EZHIP and/or histone demethylases are intimately involved in pediatric brain tumors." (PMID 40599851, 2025). "EZH2, the PRC2 catalytic subunit, is abnormally elevated in GBM cells with the highest levels in brain tumors correlating with advanced disease stages and poor prognosis." (PMID 24066060, 2013).
brain tumors (continued). "For this purpose, we queried the Oncomine database and found that 4 PcG genes (EZH2, RBBP7, SUZ12, YY1) are specifically expressed in brain tumors." (PMID 20920292, 2010). "Indeed, EZH2 was shown to be overexpressed in MBs and its inhibition is known to significantly disrupt CSC maintenance in MB and other brain tumors." (PMID 32920979, 2021). "Interestingly, the PTEN/PI3K/AKT signaling network is not the only kinase signaling cascade EZH2 interacts with among brain tumor models." (PMID 38183103, 2024).
ovarian tumors (23 papers, 2013 to 2024). "Malignant rhabdoid and ovarian tumors with SWI/SNF family member mutations are believed to be dependent on EZH2 activity and thus more sensitive to EZH2 inhibition." (PMID 30692641, 2019). "Recently, Rizzo S and colleagues reported EZH2 to be overexpressed in ovarian tumor-derived side population (SP) cells, which are stem cell-like cells enriched by chemotherapy, and demonstrated that EZH2 KD results in loss of SP cells and reduced anchorage-independent growth in ovarian tumor models." (PMID 28415635, 2017). "For instance, a peptide nucleic acid- based approach has been used to block the ability of lncRNA HOTAIR to interact with EZH2 and subsequently inhibit HOTAIR-EZH2 activity and resensitize resistant ovarian tumors to chemotherapy." (PMID 37232821, 2023). "A study reported that EZH2 degradation profoundly blocked ovarian tumor cell proliferation and tumorigenesis in vitro and in vivo." (PMID 37634008, 2023). "The pro-migratory effects of EZH2 overexpression on ovarian tumor cells involve the differential expression of multiple proteins." (PMID 36359771, 2022). "It blocked the interaction between HOTAIR and EZH2, subsequently inhibited HOTAIR-EZH2 activity and re-sensitized resistant ovarian tumors to platinum." (PMID 32370770, 2020). "EZH2 expression in ovarian tumor represses the tumor production of Th1-type chemokines CXCL9, which plays a key role in CD8+ T cell infiltration in tumors." (PMID 32723346, 2020). "ABT263 is sufficient to overcome resistance to an EZH2 inhibitor and synergizes with an EZH2 inhibitor in vivo in ARID1A-inactivated ovarian tumor mouse models." (PMID 30297712, 2018). "To determine the effects of EZH2 inhibition in vivo on the growth of CARM1-expressing ovarian tumors, we utilized two xenograft models." (PMID 29434212, 2018). "In the current study, we describe a peptide nucleic acids (PNA)-based approach to block the ability of HOTAIR to interact with EZH2 and subsequently inhibit HOTAIR-EZH2 activity and resensitize resistant ovarian tumors to platinum." (PMID 28420874, 2017). "In ovarian tumors, the overexpression of the miRNAs imposed glucose restriction on T cells, limiting the expression of the methyltransferase EZH2." (PMID 27551267, 2016). "Conversely, increased expression of EZH2 and DNMT1 in ovarian tumors was associated with decreased infiltration of CD8+ T cells and poor prognosis." (PMID 27793053, 2016). "Conversely, increased expression of EZH2 and DNMT1 in ovarian tumors was associated with decreased infiltration of CD8+ T cells and worse prognosis." (PMID 27199994, 2016). "Co-immunoprecipitation (coIP) analysis demonstrated an interaction between EZH2 and HDAC2 in ARID1A-mutated Ovarian Tumor-derived Cell Line 21G (TOV21G), and the restoration of wild-type ARID1A disrupted this interaction, suggesting that EZH2 did not interact with HDAC2 in ARID1A wild-type cells." (PMID 38794190, 2024). "Based on these data, the promoting effect of FBP1 on ovarian tumor formation and cisplatin resistance may be attributed to the up-regulation of the EZH2/H3k27me3 signaling pathway." (PMID 36000567, 2022). "Moreover, a recent work showed that EZH2 expression predicts outcome in patients with BRCA2-mutant ovarian tumors by regulating genomic stability at stalled replication forks, suggesting a possible connection between EZH2 and BRCA2." (PMID 34573332, 2021). "The levels of EZH2 in ovarian tumor negatively correlated with intratumoral CD8+ T cells." (PMID 32723346, 2020). "In addition, ABT263 synergizes with an EZH2 inhibitor in vivo in ARID1A-inactivated ovarian tumor mouse models." (PMID 30297712, 2018). "Furthermore, treatment of ovarian tumors with EZH2 and DNMT1 inhibitors increased the efficacy of tumor-associated antigen-specific CD8+ T cells in response to inhibition of the PD-1: PD-L1 checkpoint." (PMID 27793053, 2016).